ACSL5 (acyl-CoA synthetase long chain family member 5)
Description:
Catalyzes the conversion of long-chain fatty acids to their active form acyl-CoAs for both synthesis of cellular lipids, and degradation via beta-oxidation. ACSL5 may activate fatty acids from exogenous sources for the synthesis of triacylglycerol destined for intracellular storage (By similarity). Utilizes a wide range of saturated fatty acids with a preference for C16-C18 unsaturated fatty acids (By similarity). It was suggested that it may also stimulate fatty acid oxidation (By similarity). At the villus tip of the crypt-villus axis of the small intestine may sensitize epithelial cells to apoptosis specifically triggered by the death ligand TRAIL. May have a role in the survival of glioma cells.
Synonyms: ACS5; FACL5; ACS2; DIAR13
Tractability: Small molecule: a high-quality ligand is known. Antibody: UniProt places it where antibodies can reach, with high confidence; its Gene Ontology location is reachable by antibodies, with high confidence; UniProt predicts a signal peptide or a membrane-spanning region. PROTAC: ubiquitination databases record sites on it; its protein half-life has been measured; a small molecule that binds it is known.
Target class: Enzyme; Ligase
Gene: Protein-coding gene on chromosome 10 (112,372,400 to 112,428,381, forward strand). Ensembl gene ENSG00000197142.
Subcellular location: Mitochondrion; Endoplasmic reticulum; Mitochondrion outer membrane; Endoplasmic reticulum membrane; Cell membrane
Subcellular location (Human Protein Atlas): Mitochondria; Nucleoplasm
Pathways (Reactome):
Metabolism: Synthesis of very long-chain fatty acyl-CoAs
Gene Ontology:
Molecular function: long-chain fatty acid-CoA ligase activity; oleoyl-CoA ligase activity; protein binding; arachidonate-CoA ligase activity
Biological process: long-chain fatty acid metabolic process; long-chain fatty-acyl-CoA biosynthetic process; positive regulation of long-chain fatty acid import across plasma membrane; fatty acid metabolic process
Cellular component: endoplasmic reticulum; membrane; mitochondrion; plasma membrane; endoplasmic reticulum membrane; mitochondrial outer membrane
Genetic constraint (gnomAD): Loss-of-function variants: 47 observed, 85.38 expected, observed/expected ratio (o/e) 0.55, 90% interval 0.44 to 0.7. The upper end of that interval is the gene's LOEUF score, 0.7, which puts it in group 2 of 6, group 1 being the genes least tolerant of losing a copy. Missense variants: 757 observed, 857.6 expected, observed/expected ratio (o/e) 0.88, 90% interval 0.83 to 0.94. Synonymous variants: 278 observed, 314.8 expected, observed/expected ratio (o/e) 0.88, 90% interval 0.8 to 0.98.
Homologues: Orthologues: chimpanzee ACSL5 (99% identical), macaque ACSL5 (94% identical), rabbit ACSL5 (84% identical), dog ACSL5 (83% identical), mouse Acsl5 (81% identical), rat Acsl5 (81% identical), pig ACSL5 (81% identical), guinea pig ACSL5 (80% identical), tropical clawed frog acsl5 (67% identical), zebrafish acsl5 (67% identical), Caenorhabditis elegans acs-13 (48% identical), Drosophila melanogaster CG3961 (48% identical). Paralogues in human: ACSL6 (62% identical), ACSL1 (60% identical), ACSL3 (33% identical), ACSL4 (30% identical), ACSBG1 (25% identical), ACSBG2 (24% identical), SLC27A2 (19% identical), SLC27A6 (18% identical), SLC27A5 (17% identical), SLC27A4 (17% identical), SLC27A3 (17% identical), SLC27A1 (16% identical).
Diseases named in the same sentence as ACSL5 in open-access papers:
ACSL5 is named in the same sentence as 75 diseases in open-access papers, as found by Europe PMC text mining. Sharing a sentence is not in itself a finding about the gene and the disease. The quoted sentences say what the papers report.
glioma (12 papers, 2009 to 2024). A benign or malignant brain and spinal cord tumor that arises from glial cells (astrocytes, oligodendrocytes, ependymal cells). "ACSL5 dysregulation was previously reported in bladder cancer, breast cancer, glioma, glioblastomas, and pancreatic ductal adenocarcinoma." (PMID 32155177, 2020). "ACSL5 is highly expressed in glioma and drives the cell growth through midkine (MDK) in the acidic microenvironment." (PMID 27171439, 2016). "It has been shown that TC could enhance the etoposide-induced intrinsic apoptosis that is suppressed by the overexpression of ACSL5 in glioma cells." (PMID 38539505, 2024). "Previous research has shown that ACSL5 may be vital to the malignant progression and metastasis of gliomas, and this supports targeting ACSL5 as a potentially effective treatment strategy." (PMID 36733341, 2023). "This evidence demonstrated the important role of ACSL5 on glioma cell growth." (PMID 36507355, 2022). "Another long-chain ACS, ACSL5, was elevated in high-grade gliomas." (PMID 23936004, 2013). "Unlike this hypothesis, other works have shown enhanced ACSL5 expression associated to the development of colorectal cancer and involved in surviving of glioma cells under acidosis conditions, pointing to an anti-apoptotic role." (PMID 22163040, 2011). "Although ACSL5 is not common in healthy brain tissue, it is highly expressed in glioma cells and contributes to enhanced glioma survival under acidotic conditions." (PMID 36012521, 2022). "Despite their potential as targets in gliomas, no preclinical studies have developed inhibitors to selectively target ACSL1 or ACSL5." (PMID 36012521, 2022).
breast carcinoma (8 papers, 2016 to 2024). "The expression levels of ACSL1, ACSL4, and ACSL5 are regulated by the estrogen receptor signaling pathway, and ACSL5 is a potential novel biomarker to predict the prognosis of breast cancer patients." (PMID 37746665, 2023). "Cyclin T2 (CCNT2) and acyl-CoA synthetase long-chain family member 5 (ACSL5) are involved with breast cancer." (PMID 34497631, 2021). "ACSL5 is upregulated in several cancers such as colorectal cancer, ER-negative, basal and normal-like breast cancer subtypes, suggesting that the identification of specific ACSL5 inhibitors is of paramount importance." (PMID 31344914, 2019). "By contrast, downregulation of ACSL5 in breast cancer was associated with a worse prognosis and none study have been reported on the association of ACSL6 and cancer survival." (PMID 33030783, 2020).
colorectal cancer (8 papers, 2011 to 2025). A primary or metastatic malignant neoplasm that affects the colon or rectum. "The lower expression of ACSL5 is observed in the colorectal cancer tissue and the patient with the lower ACSL5 has a longer disease-free interval (DFI)." (PMID 27171439, 2016). "Downregulation of ACSL5 could be an independent prognostic factor for early recurrence of colorectal cancer, meanwhile dysregulated ALAS2 expression was related to the risk of acute myeloid leukemia." (PMID 37268653, 2023). "Reports suggest different expression levels of ACSL5 in human colorectal cancer." (PMID 31344914, 2019). "ACSLs deregulation is reported to promote cancer cell proliferation and the activity of ACSL5 and ACSL6 is often enhanced in some solid tumors like colorectal cancer." (PMID 34784264, 2022). "ACSL4 maintains a flexible role as a suppressor or an oncogene in different cancers, ACSL5 physiologically acts as a tumor suppressor in cancers, and ASCL6 is downregulated in diverse kinds of cancers, in addition to colorectal cancer." (PMID 35186949, 2021).
hepatocellular carcinoma (8 papers, 2014 to 2025). A malignant tumor that arises from hepatocytes. "Overexpression of ACSL5 in rat hepatoma cells results in acylation of exogenous fatty acids and enhances fatty acid uptake, channeling fatty acids toward anabolic pathways." (PMID 37862421, 2023). "A recent study on hepatocellular carcinoma (HCC) found that ferroptosis is regulated by the PPARGC1A/BAMBI/ACSL5 axis, with METTL3 and WTAP inhibiting PPARGC1A in an m6A- and YTHDF2-dependent manner." (PMID 40271153, 2025). "In hepatocellular carcinoma cells, high levels of TGF-β have been related to a higher expression of enzymes involved in free fatty acid synthesis such as ACSL5 and significantly higher amounts of phospholipid levels." (PMID 35574033, 2022). "First, among ACSL family members, AA treatment markedly and selectively reduced ACSL4 protein levels without affecting cellular levels of ACSL1 and ACSL5 in model hepatoma cell lines, including HepG2 and Huh7 cells as well as in primary mouse hepatocytes." (PMID 24879802, 2014). "In hepatocellular carcinoma, the hypoxia-responsive PPARGC1A (peroxisome proliferator activated receptor gamma coactivator 1 alpha)/BAMBI (bone morphogenetic protein and activin membrane bound inhibitor)/ACSL5 (acyl-CoA synthetase long chain family member 5) pathway confers lenvatinib resistance." (PMID 39935430, 2025).
lung carcinoma (5 papers, 2014 to 2024). "The upregulation of ACSL5 in the two lung cancer cell lines harboring EGFR mutations indicates a potential link between ACSL5 overexpression and EGFR mutations." (PMID 38539505, 2024). "Exogenous lysoPC altered transcriptomic profiles of lung cancer cells, of which ACSL5 was identified and validated as the target gene in lysoPC‐induced lung cancer cell hypoplasia and as a risk factor for lung cancer patient survival." (PMID 36639836, 2023). "Taken together, our data suggest that ACSL1 may be a potential diagnostic marker for lung ADC, and that ACSL1, ACSL4, and ACSL5 may be involved in lung cancer differentiation." (PMID 38539505, 2024). "The mRNA data from KM Plotter showed that ACSL1 and ACSL5 were favorable prognostic markers in lung cancer." (PMID 38539505, 2024). "ACSL5 expression correlates with improved survival in lung cancer patients, and plasma EA levels predict immunotherapy success." (PMID 39108264, 2024). "We found that, compared to normal human bronchial epithelial (NHBE) cells, ACSL1, ACSL4, and ACSL6 were highly expressed, while ACSL3 and ACSL5 were lost in the majority of lung cancer cell lines." (PMID 38539505, 2024). "Lung cancer cell sensitivity to lysoPC was evaluated and decisive roles of long‐chain acyl‐coenzyme A synthase 5 (ACSL5) in lysoPC regulation were defined by comprehensively evaluating transcriptomic changes of ACSL5‐downregulated epithelia." (PMID 36639836, 2023). "Our present study furthermore demonstrated that ACSL5 plays important role in the control of lung cancer cell sensitivity to exogenous lysoPC by reshaping participants of transcriptional regulators." (PMID 36639836, 2023). "Our data from ACSL5 knockdown and overexpression evidenced that ACSL5 was crucial for the control and maintenance of the sensitivity of lung cancer cells to exogenous lysoPC by reprogramming and regulation of TAG‐lysoPC metabolism." (PMID 36639836, 2023). "External lysoPC inhibited lung cancer cell proliferation, mitochondrial dysfunction and lipid metabolisms by increasing FA oxidation through ACSL5, while down‐regulation of ACSL5 changed lung cancer cell sensitivity in response to lysoPC." (PMID 36639836, 2023). "Of FA metabolism and ACSL family members, ACSL5 over‐expressed in lung epithelia with structural, proliferative, cleaning and secretory functions in patients with lung cancers." (PMID 36639836, 2023). "ACSL5 over‐expressed in ciliated, club and Goblet cells in lung cancer patients, different from other lung diseases." (PMID 36639836, 2023). "ACSL5 plays a critical role in lysoPC‐induced lipid metabolism in lung cancer cells, of which TAGs‐lysoPC bi‐directional metabolites were the central balance." (PMID 36639836, 2023). "There was a difference between lung carcinoma and lung adenocarcinoma that lung carcinoma expressed low level of ACSL5 and lung adenocarcinoma expressed high level of ACSL5." (PMID 27171439, 2016). "Taken together, the data suggest that ACSL1 may be a biomarker for lung ADC, and ACSL1, ACSL4, and ACSL5 may be involved in lung cancer differentiation, and TC, in combination with chemotherapy or EGFR-TKIs, may help patients overcome drug resistance." (PMID 38539505, 2024). "In human lung cancer cells, we found that the proteins of ACSL1, ACSL4, and ACSL6 were highly expressed in most of the lung cancer cell lines observed, while the proteins of ACSL3 and ACSL5 were lost in the majority of the lung cancer cell lines, compared to the NHBE cells." (PMID 38539505, 2024). "LysoPC inhibited lung cancer cell proliferation, by inducing mitochondrial dysfunction, altering lipid metabolisms, increasing fatty acid oxidation and reprograming ACSL5/phosphoinositide 3‐kinase/extracellular signal‐regulated kinase‐regulated triacylglycerol‐lysoPC balance." (PMID 36639836, 2023).
lung carcinoma (continued). "Exogenous lysoPC inhibited lung cancer cell proliferation by promoting ACSL5, leading to the disorder of FA degradation and metabolism, compromise of mitochondrial morphology and functions and reprogramming of ACSL5/PI3K/ERK‐regulated TAG metabolism." (PMID 36639836, 2023). "High expression of ACSL5 predicted good prognosis in breast, ovarian, and lung cancers." (PMID 27171439, 2016). "However, a few analyses gave the inconsistent trend in one cancer, including the outcome of ACSL3 in lung cancer of GSE13213 and GSE31210 datasets, the expression of ACSL4 in Buchholz and Badea pancreatic cancer datasets, and the expression of ACSL5 in Hou and Okayama lung cancer datasets." (PMID 27171439, 2016). "ACSL4 and ACSL5 were downregulated in the majority of lung cancer cell lines, except for an upregulated ACSL4 in H226, H2030, and H1975 and increased ACSL5 levels in COLO677, H322, H1650, and H1975, compared to the NHBE cells." (PMID 38539505, 2024). "Of them, 6 miRNAs (miR-149, miR-205, miR-375, miR-378, miR-422a and miR-708) and 9 target genes (CEACAM6, CGN, CLDN3, ABCC3, MLPH, ACSL5, TMEM45B, MUC1) were validated by quantitative PCR in an independent cohort of 41 lung cancer patients." (PMID 24625834, 2014). "Similar to the expression pattern of ACSL5, ACSL3 was lost in most of the lung cancer cell lines, and, based on the expression of ACSL3 in primary lung tumor, we consider that ACSL3 might be involved in lung ADC differentiation." (PMID 38539505, 2024). "ACSL5‐downregulated lung cancer cells had less or no sensitivities in response to lysoPC, including exogenous lysoPC‐induced alterations of mitochondrial morphology and function, long‐chain FA mitochondrial beta‐oxidation, ROS productions and those lipid metabolisms." (PMID 36639836, 2023).
bladder cancer (4 papers, 2013 to 2025). "In contrast, lower levels of ACSL5 were reported in bladder cancer." (PMID 23936004, 2013). "We constructed CHMP6 knockdown human bladder cancer cell lines and utilized WB and Q-pcr techniques for validation at the protein level and RNA level, and in the cell lines with CHMP6 knockdown, we found that ACSL5 protein levels were elevated." (PMID 40630215, 2025).
colorectal adenocarcinoma (4 papers, 2009 to 2024). The most common type of colorectal carcinoma.
fatty liver (4 papers, 2018 to 2025). "Collectively, the results suggest that ACSL1, ACSL5, EHHADH, and ACAA1 play an important role in the development of fatty liver disease in dairy goats." (PMID 40723475, 2025). "The results showed that the four genes (ACSL1, ACSL5, EHHADH, and ACAA1) were significantly upregulated in the hepatic tissues of dairy goats with fatty liver." (PMID 40723475, 2025). "Indeed, we observed significantly elevated gene expression of ACSL1, ACSL5, EHHADH, and ACAA1 in the hepatic tissues of periparturient goats affected by fatty liver disease." (PMID 40723475, 2025). "We speculate that the altered ubiquitination of ACSL1, ACSL5, EHHADH, and ACAA1 contributes to their increased hepatic protein levels and abnormal subcellular localization in dairy goats with fatty liver." (PMID 40723475, 2025). "Mice with an intestine-specific Acsl5 knockout are protected from high-fat diet (HFD)-induced obesity, insulin resistance, glucose intolerance and hepatic steatosis, and show increased GLP-1 levels, delayed gastric emptying (GE), and decreased food consumption (FC)." (PMID 41623902, 2025). "Notably, by observing the overlap among these three sub-networks, we found that proteins with downregulated ubiquitination—such as ACSL1, ACSL5, EHHADH, and ACAA1—were transcriptionally upregulated in dairy goats with fatty liver." (PMID 40723475, 2025). "Our results showed the expression of ACSL5,4,3 genes significantly decreased with the severity of hepatic steatosis, and the rate-limiting enzyme CPT1A was almost not expressed in steatotic livers (Padj < 0.05, β = 45.17, post hoc Wilcoxon rank-sum test, 67 times higher in eCtrl than eHS-II)." (PMID 38837944, 2024). "The expression levels of ACSL5, APOA4 and ME1 in F0 chickens with fatty liver were higher than those in chickens without fatty liver (p < 0.05), but the differences were highly significant in the F1 generation (p < 0.01)." (PMID 29642504, 2018).
Obesity (4 papers, 2018 to 2025). Accumulation of substantial excess body fat. "and ACSL5 in the aorta of obesity-induced mice, and there was a close relationship between the four." (PMID 39176252, 2024). "Collectively, these findings suggest that ACSL5 may serve as a potential therapeutic target for obesity and hyperlipidemia." (PMID 41288931, 2025). "Although SNPs were located on obesity-related genes, some of the genes also have a direct role in lipid metabolism including PPARG, FABP2, PLIN1, NPC1, ACSL5, and FAAH, suggesting relationships between genetics, adiposity, and plasma lipid profiles." (PMID 30581838, 2018). "Conversely, ACSL5 knockdown reduces food intake by increasing glucagon-like peptide (GLP) and peptide YY (PYY) secretion and decreasing gastric emptying rate, mitigating HFD-induced obesity and insulin resistance." (PMID 41288931, 2025).
pancreatic cancer (4 papers, 2016 to 2024). "In an effort to identify crucial biomarkers for pancreatic cancer prognosis, a study discovered a total of four genes, ACSL5, SLC44A4, LOX, and TOX3, showing correlation with PFS as indicated by qPCR and immunohistochemical staining." (PMID 39108264, 2024).
colon cancer (3 papers, 2010 to 2020). "While some studies reported that ACSL5 downregulation is associated with tumor development or early tumor recurrence, the other investigations indicated that ACSL5 overexpression plays a key role in colon cancer cells aggressiveness." (PMID 32155177, 2020). "We suppressed ACSL5 expression in HCT116 and LOVO human colon cancer cells using lentiviral shRNA." (PMID 21073737, 2010).
gastric cancer (3 papers, 2017 to 2021). A primary or metastatic malignant neoplasm involving the stomach. "ACSL5, belonging to the acyl-CoA synthetase long-chain (ACSL) family, is a nuclear-coded pro-apoptotic gene that participates in cancer suppressors; however, it shows a pro-oncogenic role in gastric cancer." (PMID 35186949, 2021).
Insulin resistance (3 papers, 2019 to 2025). Increased resistance towards insulin, that is, diminished effectiveness of insulin in reducing blood glucose levels. "However, contrary to conventional wisdom’s prediction that elevating mitochondrial fatty acid oxidation would attenuate the progression toward insulin resistance in skeletal muscle, ACSL-5 was also associated with increased free radical production (i.e., O2− ) and reduced insulin signaling." (PMID 30935113, 2019). "In addition, the related fatty acids metabolism is also enriched in the PPAR signaling pathway or insulin resistance pathway, such as Fads2, Pparg, Acsl5, Fabp1 and Acacb." (PMID 37627267, 2023). "Together, ACSL-5 overexpression may induce insulin resistance through a mechanism of increased mitochondrial ROS production in skeletal muscle." (PMID 30935113, 2019).
malignant glioma (3 papers, 2017 to 2022). A grade III or grade IV glioma arising from the central nervous system. "Accordingly, ACSL5 is up-regulated in several cancers, including colorectal, breast, bladder, esophageal, lung, pancreatic, prostate, and malignant gliomas." (PMID 34943992, 2021).